ENSG00000269867 (novel transcript, sense intronic to ZNF814)
Gene: Long non-coding RNA gene on chromosome 19 (57,867,038 to 57,868,172, reverse strand). Ensembl gene ENSG00000269867.
Gene Ontology:
Molecular function: structural constituent of ribosome
Cellular component: ribosome